TNF (tumor necrosis factor)
Diseases named in the same sentence as TNF in open-access papers (continued):
Sharing a sentence is not in itself a finding about the gene and the disease.
influenza (continued). "Moreover, decreasing levels of interferon gamma, interleukin 2, and tumor necrosis factor alpha, as well as the activation of the bradykinin 2 receptor signaling pathway, constitute potential mechanisms underlying the stabilization of atherosclerotic plaques by influenza vaccination." (PMID 35665329, 2022). "TNFα, among other pro-inflammatory cytokines, was also upregulated following influenza infection in vitro." (PMID 36405747, 2022). "Consistent with the results of our previous experiments, LS inhibited the expression of inflammatory factors such as TNF-α、IL-6、IL-1α、IFN-γ after influenza infection in vivo and in vitro." (PMID 36034844, 2022). "Specifically, influenza antigens conjugated to both 3 μm and to 500 nm particles induced higher levels of the pro-inflammatory cytokines IFNγ and TNFα in CD4+ T cells than the unconjugated particles." (PMID 35890185, 2022). "TNFα antagonism would warrant additional research about the timing of treatment administration since TNFα is potentially protective during the early stages of influenza and SARS-CoV-2 infection." (PMID 35674675, 2022). "In critically ill patients with influenza, disease severity is also related to elevated levels of TNF-α, IL-6, IL-8, and IL-10." (PMID 34987205, 2022). "These patients had a sustained production of IL-6 and TNF-α, which was unique when compared to a retrospective cohort of influenza H1N1 2009 patients." (PMID 34728719, 2021). "Several polymorphisms which have been known for the susceptibility to influenza infection include CD55, C1QBP, FCGR2A, IFITM3, TNF, RPAIN, LTA and KIR." (PMID 33766078, 2021). "The results showed that influenza infection induced significantly higher mRNA expressions of IL-1β, IL-6, TNF-α, IL-10, MCP-1, IP-10, IFN-γ, and IFN-β in lung compared with non-infection mice." (PMID 35154087, 2021). "Severe influenza is partly mediated by the cytokine storm, particularly tumor necrosis factor-α (TNF-α)." (PMID 33562193, 2021). "At the late stage of infection, L. plantarum (O6CC2) decreases IL6 and TNF-α production to control influenza-mediated inflammation." (PMID 33897683, 2021). "Patients who will receive anti-TNF (tumor necrosis factor) should be vaccinated for influenza, pneumococcus, hepatitis B, diphtheria and tetanus." (PMID 33636755, 2021). "A combination of influenza antigens with particulate TNF increased GC activities and mouse survival rates after a lethal influenza challenge." (PMID 33430259, 2021). "Soluble TNFRII released in this manner critically regulates influenza-related pulmonary inflammation by binding to and inhibiting the proinflammatory effects of soluble TNFα released within the lung." (PMID 35095853, 2021). "CD4+ TNF-α production upon influenza stimulation was observed in both TIV and LAIV recipients, regardless of colonization status, but not in unvaccinated individuals." (PMID 33497364, 2021). "Patients receiving anti-TNF monotherapy appear to have reduced protective immunity in response to hepatitis A and B as well as influenza and pneumococcal vaccinations." (PMID 34833096, 2021). "Studies characterizing vaccine-induced T-cell responses against HIV, HCV, and influenza, revealed a strong association between the level of protection and the induction of high frequencies of T cells co-producing IFN-γ, TNF-α, or IL-259–63." (PMID 33654106, 2021). "For example, in case of influenza infection, a positive feedback loop involves the production of IL-1 and TNF by macrophages in response to granulocyte-macrophage colony-stimulating factor released by nonhematopoietic cells." (PMID 33536217, 2021). "Herein, our network study identified three main pathways associated with curcumin and influenza: PI3K/AKT, TNF, and MAPK signaling pathways." (PMID 34577580, 2021). "MC-derived cytokines of potential interest in suppressing influenza immunopathology include: TNFα, TGF-β1, GM-CSF, IL-2, IL-9, IL-13, and IL-33." (PMID 33680987, 2021).
influenza (continued). "It has been shown that influenza upregulates TNF-α, interleukin (IL)-1β, and IL-6 and that these cytokines increase trypsin expression in endothelial cells." (PMID 33562193, 2021). "Influenza infection stimulates cytokine responses in patients, represented as heightened levels of tumor necrosis factor (TNF)-a and interleukin(IL)-6, activating platelets and forming aggregates with immune cells (e.g., neutrophils and monocytes)." (PMID 34059141, 2021). "Influenza vaccination led to significantly higher TNFα production upon Influenza and poly(I:C) stimulation." (PMID 34695164, 2021). "Tumor necrosis factor-α (TNF-α) and interleukin-6 (IL-6) production by circulating monocytes were persistent, a complex pattern different from influenza or bacterial sepsis." (PMID 33747973, 2020). "Since the lowest influenza vaccine responses in IBD patients are reported in patients using combination therapy with an anti-TNFα agent and an immunomodulatory agent, this would have been an interesting addition." (PMID 32824111, 2020). "In this prospective study, we assessed immune responses to seasonal influenza vaccination in CD patients treated with ustekinumab compared to CD patients treated with anti-TNFα therapy (adalimumab) and healthy controls." (PMID 32824111, 2020). "RANTES, IL-1β, IL-6, and TNF-α induced by influenza result in pro-inflammatory Th1-type immune responses in the infected host." (PMID 32269562, 2020). "Because of its cytotoxic and pro-inflammatory effects, TNF-α plays a dual role (beneficial and harmful to the patient) during influenza infection." (PMID 33374214, 2020). "Inhibiting TNF-α signaling leads to increased survival outcomes and decreased lung damage following lethal dose influenza infection." (PMID 32974217, 2020). "Many influenza-induced cytokines, such as IL-1β and TNF-α, act both as potent activators of NF-κB and are themselves NF-κB target genes, indicating the potential for uncontrolled feed-forward inflammatory activation." (PMID 33239293, 2020). "Several ways to improve the influenza vaccination response during anti-TNFα therapy have been investigated." (PMID 32824111, 2020). "In contrast, human PBMC cultured with influenza vaccine and inflammatory cytokines (IL-1, IL-6 and TNF) showed a suppressed T cell response to a subsequent influenza challenge." (PMID 32399058, 2020). "Influenza also induces epithelial cell release of a variety of cytokines and chemokines, including TNFα, IL-8, IL-6, CCL2, CCL5, CXCL1, and CXCL10, which attract macrophages and neutrophils to the infection site." (PMID 33193350, 2020). "Several previous studies have shown decreased immune responses to influenza vaccination in IBD patients using anti-TNFα agents." (PMID 32824111, 2020). "and tumor necrosis factor α (TNFα) were identified as being involved in influenza-induced inflammation." (PMID 32854331, 2020). "Treatment with exogenous SP-A decreases influenza infection and the production of inflammatory cytokines including TNF-α, IL-6 and IFN-γ." (PMID 33542724, 2020). "Elevated levels of the pro-inflammatory cytokine, tumor necrosis factor-α (TNF-α) have been reported in the placenta, amniotic fluid, and the brain of the fetus from mothers with influenza infection." (PMID 33005129, 2020). "TNF-α is expressed in the lung epithelial cells in response to respiratory viruses, such as influenza, and it recruits lympho-monocytes in the site of infection." (PMID 33276686, 2020). "TNF-α secreted by NK cells and T cells contributes significantly to the pro-inflammatory cytokine response during influenza." (PMID 32974217, 2020). "CD8+ T cells produce significant amounts of TNF-α; binding of inhibitory receptor NKG2A on T cells is important in limiting excessive production of TNF-α during influenza infection." (PMID 32974217, 2020). "Therapeutic blockade of TNF-α signaling improves morbidity and mortality outcomes following lethal dose influenza infection in mice." (PMID 32974217, 2020).
influenza (continued). "A pro-inflammatory immune response to influenza and pneumococci is accompanied by the induction of IL-1, IL-6, TNF-, RANTES, MIP-1-alpha, IL-8, IL-10 and gamma interferon." (PMID 31513620, 2019). "Influenza infection induces a variety of inflammatory cytokines and chemokines such as IL-6, IL-8, TNFα, CCL2, CCL5, CXCL10, and recruitment of neutrophils and macrophages to clear the virus." (PMID 31159430, 2019). "Although reconstituted ILC1s did not display functional activation with regard to the secretion of IFN-γ and TNF-α upon influenza infection at the investigated time points, increased expression densities of TRAIL and CD49a on ILC1s were detected." (PMID 29623077, 2018). "Influenza infection induced a variety of inflammatory cytokines such as IL-1β, IL-6, TNFα, IL-8, CCL2, CCL5, and CXCL10 from epithelial and immune cells." (PMID 30337919, 2018). "Maternal immune activation (e.g., via an infectious exposure such as influenza) has been reported to be associated with risk of SZ and autism, and blood levels of cytokines (e.g., IL1B, IL2RA, IL-6, and TNF) are elevated in SZ patients (see reviews)." (PMID 30115913, 2018). "TNF-α was indicated to be beneficial early during influenza infection either by a direct antiviral effect on lung-epithelial cells or by activating macrophages and inducing DC maturation." (PMID 29623077, 2018). "We found an increase in the levels of the inflammatory cytokines IL-1α, IL-1β, TNFα, IL-6, IL-12p40, IL-17, and IFNγ, and increased levels of the Type 2 cytokines IL-4 and IL-5, in influenza-infected Stat2−/− mice when compared to WT mice." (PMID 30337919, 2018). "Influenza infections in bone marrow-derived macrophages of CLEC5A−/− mice showed reduced levels of TNF-α and IP-10 but increased IFN-α compared WT mice." (PMID 27795434, 2017). "These molecules, along with TNF and IL1b (also over-expressed at day 5), are the major cytokines limiting viral replication during influenza infection, recruiting immune cells to the sites of infection and producing inflammation." (PMID 29038764, 2017). "TNF-α is known to be able to induce epithelial cells to secret GM-CSF to promote tissue repair and to enhance monocyte transmigration during influenza infection." (PMID 28622363, 2017). "Specifically, monocytes (macrophage precursors) obtained from older adults prior to influenza vaccination exhibit impaired function with decreased TNF-α and IL-6 secretion, but intact IL-10 responses." (PMID 28769922, 2017). "It has been shown that global TNF/TNFR2 signaling inhibits the secondary CD8+ T cell response to influenza in the lungs." (PMID 28886201, 2017). "TNF is one of the major mediators of inflammation and its role during influenza infections has been described in several studies." (PMID 28886201, 2017). "In response to influenza A virus-infection, macrophages produce large amount of cytokines such as IL-6, TNF-α, and MCP-1." (PMID 28352642, 2017). "Studies investigating the role of TNF in anti-influenza immune responses, viral clearance and immunopathology have indicated that TNF is not required for viral clearance in the lungs, but is essential in controlling lung damage." (PMID 28886201, 2017). "Four pediatric studies have evaluated influenza vaccine in JIA patients receiving anti-TNF-α therapy." (PMID 28784185, 2017). "Influenza induces expression of cytokines, i.e., TNFα, IL-1β and IFN-β and chemokines such as KC (murine IL-8) that is inhibited by Eritoran therapy." (PMID 28106157, 2017). "We were particularly interested in IL-2, IL-12p70, IFN-γ, IL-1β, IL-10, IL4, and TNF-α, given their involvement in the immune response during influenza infection and also given the phenotype of the response upon vaccination." (PMID 28792466, 2017). "FP7 led to a significant reduction in influenza-induced gene expression for TNF-α, IL-1β, IFN-β, KC (P < 0.01), IL-6, and RANTES (P < 0.05)." (PMID 28106157, 2017).
influenza (continued). "Our results showed that indirubin treatment lessened the production of TNF-α, IL-1β and IL-6 while enhanced the production of IL-10 in the lung tissues of influenza-infected mice loaded with stress." (PMID 29285277, 2017). "On the other hand, Eotaxin, MIG, IL-6 and TNF-α, which are pro-inflammatory and chemoattractant responses that are induced by influenza infection, peaked early in the vaccinated group at 3 days post infection but then declined by 7 days post infection." (PMID 29267331, 2017). "Specifically, it has been shown that pDC stimulation with enveloped viruses, such as herpes simplex or influenza, results in the production of the inflammatory cytokines TNF-α and IL-6, as well as ß chemokines such as MIP-1α and MIP-1ß." (PMID 26871575, 2016). "This idea is consistent with a report which demonstrated that pretreatment of influenza-infected mice with 1-MT, increased inflammatory markers, such as IL-6, TNF-α and IFN-β, and Th1 cell numbers and boosted the secondary immune response." (PMID 27695127, 2016). "In influenza-infected mice, B cell precursors transiently decreased in numbers in a TNF- and LT-dependent manner." (PMID 27695457, 2016). "TNF-α and IL-1β are important proinflammatory cytokines and contribute directly to the severity of gross and histologic lung lesions in the influenza infected mice." (PMID 27110056, 2016). "A dominant co-production of IFN-γ and TNF-α was also shown for human CD8+ T cells responding to influenza peptide restimulation." (PMID 25971313, 2015). "We focused on IFN-γ and TNF-α because they are very important for a successful immune response during influenza infection." (PMID 25915748, 2015). "In a previous study performed by our team, several single-nucleotide polymorphisms (SNPs) associated with the risk of influenza infection, including CCL1 rs2282692, LTA rs909253, and TNF 1800750, were identified in a population in Mexico City." (PMID 26657940, 2015). "Phagocytosis is clearly important in limiting the spread of virus in the lungs during the early stages of influenza infection, but prolonged release of pro-inflammatory cytokines such as TNF-α results in excessive inflammation and pulmonary damage." (PMID 26393920, 2015). "A previous study demonstrated that the depletion of TNF-α in influenza or respiratory syncytial virus-infected animals significantly reduced pulmonary inflammation and cytokine production, without compromising viral clearance." (PMID 25888728, 2015). "We found that in H1N1-inoculated mice, anti-HMGB1 mAb significantly suppressed the local production of IL-6 and TNF-α, key cytokines orchestrating the pathophysiology of highly virulent influenza strains." (PMID 26067826, 2015). "For inactivated influenza and x31/Ova cohorts, modest cytokine induction was observed characterized by IL-6 and tumor necrosis factor alpha (TNF-α) transcript upregulation." (PMID 26161083, 2015). "During infections like influenza, symptoms are generally ascribed to the action of cytokines (like IL-1, IL-6, tumor necrosis factor alpha (TNF) and interferons)." (PMID 26438161, 2015). "Severely ill patients (n = 12) had significantly higher numbers of influenza specific T-cells secreting TNF-α than moderately ill patients (n = 12)." (PMID 26606759, 2015). "We used the predictive power of MHC-binding algorithms accessed through IEDB in identifying MHC-II ligands for three commonly used anti-TNFα biologics and influenza HA." (PMID 26270649, 2015). "Key steps in establishing the importance of TNF in sleep were its suppression by an anti-TNF antibody and both spontaneous and influenza-induced sleep being variously altered in double TNF receptor-deficient mice." (PMID 24655719, 2014). "TNF-α level has been found to correlate directly with the severity of gross and histologic lung lesions in the influenza infected mice." (PMID 24725777, 2014).
influenza (continued). "We have previously shown that TNF-α production by influenza-specific CD8+ T cells is critical for the development of severe and lethal lung injury during influenza infection." (PMID 25251060, 2014). "We therefore examined the ex vivo capacity of NKG2A−/− influenza-specific CD8+ T cells to produce TNF-α in-vitro by peptide stimulation." (PMID 25251060, 2014). "The mechanisms by which expression of TNF-α by influenza-specific CD8+ T cells mediate this lethal injury are through the induction of chemokines by alveolar epithelial cells and the subsequent recruitment of inflammatory cells into the lungs." (PMID 25251060, 2014). "TNF-α, which is generally considered to be a proinflammatory and proimmune cytokine, plays an important role in the early stages of host defense against influenza infection." (PMID 24676272, 2014). "In agreement, it was recently shown that EE housing attenuates the increase in hippocampal TNFα levels in a mouse model of influenza infection, and decreases lipid peroxidation after transient middle cerebral artery occlusion in rats." (PMID 25004165, 2014). "In influenza infection, IL-1β bind with its receptors leads to the activation of multiple cytokines, including TNF-α which plays an important role in the early stages of host defense against influenza infection." (PMID 25547136, 2014). "Surprisingly, the triple combination of IFNβ, TNFα, and IL1β reduced influenza-induced cell death in infected DCs." (PMID 24616721, 2014). "In both the cross-sectional study and the recent-infection study, qualitatively different responses, i.e. increased numbers of IFNγ−IL-2+TNFα+ cells, occurred against the peptides from the recent influenza CA/09." (PMID 23526940, 2013). "Increased production of specific inflammatory cytokines, such as the tumor necrosis factor (TNF)-α, interleukin- (IL-) 1, IL-6, and IL-10, is characteristic during an influenza infection." (PMID 24066256, 2013). "In this study we have demonstrated that immune activation and the proinflammatory cytokine TNFα can have a detrimental effect on influenza vaccine responses in aging HIV-infected post-menopausal women." (PMID 24236161, 2013). "In summary, blocking TNF-α by using etanercept suppressed the immunopathology and mortality in lethal influenza-infected mice." (PMID 24373231, 2013). "BAL cells and PBMCs from carriage negative volunteers were stimulated with pneumococcal antigens (HK-6B or 6B c/s) or influenza and cytokine (TNF, IL-17A or IFNγ) producing CD4+ memory T-cells were subsequently detected by ICS and flow cytometry." (PMID 23555269, 2013). "Antibody neutralization of TNF-α during influenza infection has revealed that it is possible to reduce pulmonary infiltration and pathology and improve survival without impairing virus clearance." (PMID 24223177, 2013). "In mice, genetic deletion of Cnr2 exacerbated contact allergic inflammation and influenza-induced excessive airway injury possibly via induction of pro-inflammatory and pro-remodeling mediators (IL-17, IL-13, TNF-α, GM-CSF)." (PMID 23844029, 2013). "• Blocking TNF-α markedly inhibited the burst of major inflammatory cytokines (for example, IL-6, IFN-γ, and TNF-α) in the lung tissue of influenza-infected mice." (PMID 24373231, 2013). "• TNF-α inhibitor etanercept significantly improved survival and limited the lung inflammation in lethal influenza-infected mice." (PMID 24373231, 2013). "There were striking increases in influenza-specific TNFα+, IFNγ+, and IL-2+ cells in the post-infection samples." (PMID 23526940, 2013). "Blocking TNF-α resulted in improved survival and alleviated lung inflammation in influenza-infected mice." (PMID 24373231, 2013). "We have previously shown in mice that CD8+ T-cell expression of TNF-α is required for severe and lethal lung injury following recognition of an influenza antigen expressed by alveolar epithelial cells." (PMID 24223177, 2013).